CGAS (cyclic GMP-AMP synthase)
Diseases named in the same sentence as CGAS in open-access papers (continued):
Sharing a sentence is not in itself a finding about the gene and the disease.
tumor (continued). "Studies using colon and melanoma tumour models demonstrated the role of 5‐FU in lowering tumour burden by activating the cancer cell's intrinsic cyclic GMP‐AMP synthase and the cyclic GMP‐AMP receptor stimulator of interferon genes (cGAS‐STING) pathway, which in turn triggers anti‐tumour activity." (PMID 39308084, 2025). "Radiotherapy and chemotherapeutic agents induce DNA damage, leading to cytosolic double-stranded DNA (dsDNA) accumulation, which activates the cGAS-STING pathway to enhance tumor antigen presentation, immune recruitment, and tumor microenvironment (TME) remodeling." (PMID 40052963, 2025). "In the context of cancers, the cGAS-STING pathway can exert dual roles: on the one hand, it promotes anti-tumor immunity by enhancing antigen presentation, stimulating T-cell responses, and inducing direct tumor cell apoptosis." (PMID 40052963, 2025). "Moreover, DNA fragments originating from both the nucleus and mitochondria activate the cGAS-STING pathway, thereby initiating anti-tumor immune responses." (PMID 40236810, 2025). "In our study, patients with stage IB-IIIB NSCLC were treated with platinum-based NACT preoperatively, and we examined the expression of immune markers related to the cGAS-STING pathway and the density of tumor-infiltrating lymphocytes in tumor tissues before and after NACT, respectively." (PMID 38425343, 2024). "Therefore, targeting the cGAS-STING-TBK1 pathway with agonists to “heat up” the tumor microenvironment by secreting interferons and other cytokines can enhance anti-tumor immune responses." (PMID 40018367, 2024). "Consequently, IL-2 produced by infiltrating lymphocytes stimulates tumor STAT5A signaling, which, in turn, synergizes with TET2 to epigenetically elevate tumor cGAS expression, thereby establishing a positive feedback loop." (PMID 39107856, 2024). "We observed that tumor exosomal ENPP1 can hydrolyze 2′3′‐cGAMP to inhibit cGAS‐STING signaling, regardless of the concentration of exosomes." (PMID 38498770, 2024). "In this study, we show that the intrinsic cGAS signaling enhances the antitumor ability of NK cells after Mn2+ administration, independent of cGAMP from tumor cells." (PMID 39206412, 2024). "This suggests that cGAS-STING signaling in the microenvironment, or even a STING-independent mechanism in the tumor or its microenvironment, may be contributing to the observed intratumoral immune response." (PMID 38659582, 2024). "The cGAS-STING signaling pathway has been extensively studied and adopted for tumor immune therapy." (PMID 39125107, 2024). "Currently, the cGAS-STING pathway has demonstrated great potential in overcoming drug resistance and enhancing anti-tumor immunity, which can be activated by STING agonists or drugs related to the activation pathway, thus playing an important role in immunotherapy." (PMID 38566036, 2024). "The type I IFNs driven by activation of cGAS-STING signaling pathway play a pivotal role in immune modulation for it not only amplifies the antigen-presenting function but also boosts CD8+ T cells activity, supporting anti-tumor immunity." (PMID 38323315, 2024). "When cytoplasmic DNA is increased, this is more likely to activate the cGAS‐STING pathway when cells are exposed to external insults such as radiotherapy, which has been clearly demonstrated to play an active and important role in anti‐tumour immunity." (PMID 39030903, 2024). "Here the authors show that gain-of-function mutant p53s predispose cells to chromosomal instability by targeting MCMs, leading to activation of a cGAS-STING-non-canonical NF-κB signaling that promotes tumor metastasis and immunosuppression." (PMID 38167338, 2024). "By the same token, adoptively transferred tumor-infiltrating lymphocytes may have a better chance of penetrating the tumor mass and staying active due to a more hospitable TIME created by constitutive cGAS-STING activation." (PMID 39050705, 2024).
tumor (continued). "On the other hand, the activation of the cGAS-STING signaling pathway may be detrimental for the spread and replication of the virus within the tumor." (PMID 38921005, 2024). "Over the last decade, the cGAS/STING pathway has received significant attention in the cancer field as it plays a pivotal role in mounting anti-tumor responses both in a tumor cell autonomous and non-autonomous manner." (PMID 39544936, 2024). "Yet, mounting evidence indicates that cGAS-STING pathway might provoke inflammation, leading to tumor transformation, development and metastasis in certain diseases." (PMID 38510490, 2024). "Additionally, the cGAS‐STING pathway, which can be activated by diverse immunogens within the tumor microenvironment, appears to be broadly engaged." (PMID 39236316, 2024). "The complexity of interactions and the influence of the cGAS-STING pathway across different cell types create a multifaceted and dynamic environment, complicating the understanding of individual contributions to tumor behavior and response to therapies." (PMID 38523155, 2024). "Manganese can activate the cGAS-STING signaling pathway and induce an anti-tumor immune response." (PMID 38675217, 2024). "After internalization by tumor cells, PDPA triggers the endosomal escape of payload through the proton sponge effect, and then releases KLA in a GSH‐riched intracellular environment, ultimately inducing mtDNA leakage to activate the cGAS‐STING pathway." (PMID 38233164, 2024). "The cGAS–STING signaling axis is pivotal in cellular recognition of cytoplasmic DNA, playing a key role in shaping immune responses to pathogens, enhancing anti-tumor immunity, and regulating autoimmune reactions." (PMID 39518096, 2024). "Indeed, anti-tumor immunity in MMRd cancers also depends on the magnitude of cGAS/STING activation and subsequent expression of CCL5 and CXCL10 in the tumor microenvironment (TME), which influences CD8+ T and NK cell infiltration." (PMID 39544936, 2024). "This review provides an overview of the cGAS/STING pathway, its divergent roles in tumour elimination and tumorigenesis, and reported approaches to activating cGAS/STING signalling as a means of driving tumour elimination." (PMID 39403376, 2024). "Moreover, TFAM‐related mitochondrial dysfunction was confirmed to further activate the downstream cGAS‐STING axis, which was well‐documented to function a suppression effect on OSCC and many other tumours." (PMID 39169452, 2024). "The results clearly showed that the stimulation of tumor promoters, such as EGF and bFGF, increased anchorage-independent cell transformation and cancer cell colony growth in cGAS-wt overexpressing cells compared to that of cGAS-mt overexpressing cells." (PMID 39424777, 2024). "Recent studies have shown that chemotherapy can activate the cGAS-STING pathway in cancer cells, leading to an innate immune activation and recruitment of immune cells to the tumor microenvironment, which may contribute to the antitumor effects of these drugs." (PMID 39177280, 2024). "The cGAS-STING activation shows powerful and positive effect on strengthening the T cells-mediated anti-tumor immunity and reversing M2 macrophage-mediated tumor immunosuppressive microenvironment by secreting type I interferon and various inflammatory cytokines." (PMID 38831378, 2024). "Furthermore, HCC patients with high tumor TET2, p-STAT5A, cGAS, LRRC8C, and endothelial STING expression had better clinical outcome." (PMID 38177099, 2024). "Furthermore, we demonstrated that MSC‐induced NK resistance in cancer cells was related to an intercellular loop of cGAS‐STING‐IFNβ‐HLA signaling, consistent with the findings of clinical tumor sample analysis." (PMID 38638003, 2024). "Moreover, the expression of cGAS and STING is notably low in tumor cells from several cancer types, particularly in central nervous system (CNS) tumors." (PMID 38226619, 2024).
tumor (continued). "In vitro and in vivo experiments confirmed that LEV@DOX@REV could activate the cGAS/STING signal pathway and ICD, activate immune cells, and release cytokines, thus leading to tumor apoptosis through chemotherapy combined with immunotherapy." (PMID 38868091, 2024). "Deletion of cGAS or STING diminishes DNA sensing and lead to progressive tumor growth." (PMID 38168435, 2024). "Tumors exhibiting cGAS positivity are characterized by elevated concentrations of T-cell-derived effector cytokines, such as IFN-γ and TNF-α, and demonstrate enhanced responsiveness to ICIs, indicative of a “hot” tumor phenotype." (PMID 38817608, 2024). "In addition, the expression levels of cGAS and TMEM173 (the STING gene) mRNA in many tumor tissues (such as breast, head, neck, lung, and pancreatic cancer) were increased (compared with levels in normal tissues)." (PMID 38525112, 2024). "The cGAS-STING pathway, an important component of the innate immune system, plays a key role in defending against viral and bacterial infections, modulating cellular damage, inflammatory responses, autophagy, and tumor immunity." (PMID 39737190, 2024). "The cGAS-STING pathway, by sensing damaged cytoplasmic DNA, activates DCs, promotes IFN-I secretion, upregulates PD-L1 expression on tumor cell surface, promotes antigen presentation by APC, increases CD8+ T lymphocyte infiltration, regulates TME, and connects innate and cellular immunity." (PMID 38425343, 2024). "Through activation of the cGAS/STING pathway, chemotherapy drugs and reversine (REV) may provide synergetic anti-tumor effects." (PMID 38868091, 2024). "This paradox may be due to sustained low-level activation of cGAS/STING, which maintains chronic pro-tumour inflammation." (PMID 39403376, 2024). "Additionally, cGAS/STING-induced pro-inflammatory chemokines and cytokines have a wide range of immune-stimulatory effects shown to induce potent anti-tumor responses." (PMID 39544936, 2024). "Therefore, personalized therapeutic strategy should be taken into account due to the different response to cGAS-STING agonists of HPV subtypes and tumor microenvironment." (PMID 39295867, 2024). "By triggering cGAS-STING signal transduction, PARPi induces downstream IFN-I signal transduction and lymphatic attractant chemokines such as CCL5 secretion, which increases the expression of PD-L1 on the surface of tumor cells induced by IFN-γ." (PMID 38566036, 2024). "In a xenograft tumor model, treatment of IFN‐β or IFN‐γ inhibited tumor growth of wild‐type but not cGAS‐ or IRF3‐deficient B16‐F10 cells." (PMID 39004913, 2024). "By blocking CD47, the capacity of CD103+ DCs to take up tumor DNA is increased, thereby promoting the secretion of CXCL9 and IL-12, activating the cyclic GMP-AMP synthase (cGAS)-stimulator of interferon genes (STING) pathway, and facilitating the recruitment and activation of NK cells within HCC." (PMID 39726605, 2024). "Studies have revealed that chromosomal instability leads to the release of cytoplasmic DNA, activating the cGAS-STING signaling pathway and enhancing tumor cell metastatic capability, indicating that chromosomal instability (CIN) is also a potent regulator of cGAS-STING signaling in cancer cells." (PMID 39295867, 2024). "The cGAS-STING pathway also plays a vital role in tumorigenesis and tumor development." (PMID 38515746, 2024). "Notably, we observed activation of the cGAS-STING pathway upon combination treatment, subsequently activating the function of CD8 + T cells and resulting in a robust, tumor-specific immune response and the induction of abscopal effects." (PMID 39285178, 2024). "Gajewski and colleagues elegantly described the role of cGAS-STING pathway activation in cancer, emphasizing how cancer outcomes are influenced by the successful priming of T cells by activated antigen-presenting cells in the tumour microenvironment." (PMID 39271762, 2024).
tumor (continued). "However, the crosstalk of cGAS-STING pathway between tumor cells and host cells in tumor microenvironment remains largely unclear." (PMID 38177099, 2024). "It plays a crucial role in facilitating the secretion of cGAS-STING1-dependent type I interferons, which have an important role in the differentiation of both CD8+T cells, CD4+T cells and NK+ cells, as well as in immune-mediated suppression of tumour growth." (PMID 39723259, 2024). "One study demonstrated that delivering DNA-damaging drugs to the cell nucleus could activate hnRNPA2B1, which, through a downstream cGAS-dependent pathway, promotes the production of IFN-β, mediating an anti-tumor effect." (PMID 38523155, 2024). "Given these dual but opposing roles (i.e., anti-tumorigenic vs. pro-tumorigenic roles) of the cGAS-STING pathway, understanding how this pathway is regulated in tumor cells to lead to different outcomes is very important for studies of tumorigenesis and tumor progression." (PMID 38167338, 2024). "While transient activation of cGAS-STING within innate immune cells could enhance antitumor efficacy, prolonged activation may lead to immune tolerance, thereby promoting tumor progression." (PMID 38817608, 2024). "Additionally, activation of the cGAS/STING downstream pathway leads to an increase in IFN-I production and TNF production, the 2 factors combined that lead to an anti-tumor response." (PMID 38868091, 2024). "As the cGAS/STING pathway is frequently suppressed or defective in a variety of cancers, the anti-tumor activity of FOLFOX, anti-PD-1/PD-L1 or their combination may show reduced efficacy in patients with defective cGAS/STING signaling." (PMID 39469633, 2024). "When tumors were inoculated into unimmunized cGAS−/− and wild‐type mice, no discernible differences in tumor growth were observed." (PMID 38900071, 2024). "However, the cGAS-STING pathway is a double-edged sword, and its activation can enhance anti-tumor immunity and immunosuppression." (PMID 39464890, 2024). "DDIR-positive tumours (exhibiting defective DNA damage repair) are characterized by an inflammatory tumour microenvironment (TME), up-regulation of interferon signalling genes, high lymphocytic infiltration, and enhanced signalling through the cGAS/STING pathway." (PMID 38744099, 2024). "The dual activation of the cGAS-STING pathway by BIBR1532 presents an intriguing avenue of research, providing a novel direction for triggering ferroptosis and activating the STING pathway to foster anti-tumour immunity." (PMID 38816831, 2024). "With intracytoplasmic DNA, cGAS-STING agonist can increase the production of interleukin 6 (IL-6), tumor necrosis factor (TNF) and interferon (IFN) and play a regulatory role in inflammation and tumor treatment." (PMID 39125107, 2024). "Additionally, the combination of cisplatin and irinotecan enhances the secretion of IL‐1β, IL‐8 and CXCL10 through the cGAS pathway, which promotes the infiltration of CD8+ T cells and dendritic cells, effectively inhibiting tumour growth." (PMID 39270064, 2024). "Furthermore, the group illustrated that DNA derived from tumor cells activates IFN-β production and DCs via the cGAS, STING, and IRF3 pathways." (PMID 38512518, 2024). "Given the correlation between activation of cGAS/STING signaling and type I interferon innate immune responses, we next sought to assess the effects of Olaparib in combination with CDC7 inhibition on anti‐tumor immunity in vitro." (PMID 39412086, 2024). "Additionally, cGAS-STING activation enhances natural killer (NK) cell activation, cytotoxicity, and antitumour effects in many tumour models independently of CD8 + T cells (orange panel)." (PMID 39271762, 2024). "The cGAS-STING pathway inhibits M2 macrophage polarization and promotes anti-tumor immunity." (PMID 39464890, 2024). "Consequently, cGAS-STING signaling is important for priming, activation and infiltration of tumor-specific cytotoxic T cells." (PMID 38660307, 2024).
tumor (continued). "Type I IFNs produced by activation of the cGAS-STING pathway instigate the differentiation and maturation of antigen-presenting cells (APCs) and the expression of MHC molecules, thereby facilitating enhanced tumor antigen presentation." (PMID 38660307, 2024). "Several studies have found that classical anticancer therapies such as radiotherapy, chemotherapy, and targeted therapy may activate the cGAS–STING signaling pathway, thus providing an indirect STING agonist for tumor treatment." (PMID 38525112, 2024). "Activation of the cGAS-STING pathway in tumors may induce the expression of immune checkpoint molecules, suppressing the recognition and killing of tumor cells by immune ones." (PMID 38999073, 2024). "Based on the epigenetic regulation of tumor cGAS by TET2 synergized with STAT5A signaling, stimulating TET2 activity by VC triggers tumor cGAS-cGAMP-endothelial STING pathway activation and induces tumor vascular normalization, thereby potentiating immunotherapy efficacy." (PMID 38177099, 2024). "Additionally, cGAS-STING pathway activation within DCs retards lysosomal acidification, impeding the clearance of tumor antigens." (PMID 39834588, 2024). "Cyclic GMP-AMP synthase (cGAS) discerns free DNA and activates the stimulator of interferon genes (STING), subsequently culminating in the secretion of cytokines and exerting inhibitory effects on tumor development." (PMID 39834588, 2024). "In addition, Olaparib treatment has been shown to enhance cGAS/STING signaling in tumor cells and dendritic cells through the increase in PARPi-induced cytosolic DNA in tumor cells." (PMID 39062190, 2024). "Especially, we discovered ESYT3 as a tumor suppressor and a novel radioimmune response sensitizer for LUAD, which can activate cGAS-STING-dependent DNA damage response through directly interacting with STING, acting as a potential treatment target for improving LUAD prognosis." (PMID 39103908, 2024). "Additionally, RT can activate the cGAS-STING pathway within tumor cells, leading to the production of IFN-I, which can further enhance the immune response against the tumor." (PMID 39285178, 2024). "A recent study reported that DAPK3 might drive tumor‐intrinsic immunity through the cGAS‐STING‐INF‐β pathway, which has been increasingly highlighted as a central interface between the cellular DDR system and tumor immunity." (PMID 39254643, 2024). "It remains to be determined in cancer cells treated with ST-401 that present low levels of chromosome missegregation might trigger the cGAS-STING pathway, which would also complement its tumor killing activity." (PMID 38730481, 2024). "The cGAS–STING signaling pathway has a pivotal function in immune activation, and numerous reports provide evidence that the cGAS–STING pathway plays a vital role in inhibiting tumor progression, for which many immunotherapies have been developed." (PMID 38525112, 2024). "More excitingly, mice cured by cGAS and ICB exhibited resistance to tumor rechallenge, indicating that this combination therapy could elicit effective and long-lasting immune memory that protected the mice from tumor relapse." (PMID 38518087, 2024). "In this study, to investigate the role of the tumor cell-intrinsic cGAS–STING pathway in the immune-active TME of dMMR GC, we assessed the tumor cell-intrinsic expression of cGAS–STING between pMMR/EBV (−) and dMMR GCs through immunohistochemistry (IHC) analysis of our own GC cohort." (PMID 39242811, 2024). "Moreover, tumor exosomal ENPP1 disrupts 2′3′‐cGAMP transfer from paracrine tumor to bystander THP1‐Lucia ISG cells, which inhibited cGAS‐STING signaling in immune cells." (PMID 38498770, 2024). "Moreover, TREX1 is capable of degrading tumor-derived DNA in the cytoplasm, thereby compromising the IFN-dependent antitumor immunity induced by the cGAS-STING pathway." (PMID 38877472, 2024).